IL21R (interleukin 21 receptor)
Diseases named in the same sentence as IL21R in open-access papers (continued):
Sharing a sentence is not in itself a finding about the gene and the disease.
colitis (continued). "However, Trbv and Il21r were upregulated, but their roles in the colitis rats fed with the GLP diet remained unclear." (PMID 30814921, 2019). "Similarly, IL-21 was highly expressed in the colons of C57BL/6 mice with dextran sulfate sodium (DSS)-induced colitis and Il21r-/- mice manifested milder DSS-induced colitis as compared with their WT counterparts." (PMID 30818341, 2019). "Despite recent advances in our understanding of the mechanisms underpinning the regulation of proinflammatory immune responses by the IL-21/IL-21R signaling axis, it remains unclear how this pathway or its downstream molecules contribute to inflammation during bacterial-induced colitis." (PMID 38498592, 2024). "The findings of the current study indicated that murine hosts lacking the IL-12/IL-12Rβ2 axis downstream of IL-21/IL-21R signaling and their littermate controls were equally susceptible to colon infection, yet Il12rb2−/− mice exhibited attenuated C. rodentium–induced colitis." (PMID 38498592, 2024). "Using a murine model of Citrobacter rodentium infection, we found the requirement of a functional IL-21/IL-21R signaling axis in the control of enteric microbial infections via augmenting activation of STAT1 in mucosal CD4+ T cells in a murine model of Citrobacter rodentium colitis." (PMID 30818341, 2019). "The discrepancy between colitis studies with IL-21 or IL-21R−/− mice may be due to variability in microflora between laboratories, T cell dependency in the model setup, or a consequence of transcriptional changes in the areas around the targeted gene in the k.o. mice." (PMID 29849593, 2018). "The findings of the current study provide novel insights into the mechanisms by which functional IL-21/IL-21R signaling regulates IL-12 responsiveness by promoting IL-12Rβ2 expression in CD4+ T cells, leading to colitis." (PMID 38498592, 2024). "As such, the lack of an intact IL-21/IL-21R signaling axis in mice (Il21r−/−) resulted in attenuated inflammatory responses and reduced colitis in a murine model of human IBD." (PMID 31867283, 2019). "In our facility, IL-21R−/− mice are not protected from DSS-induced colitis neither in an acute nor in a chronic setup." (PMID 29849593, 2018). "Like human IBD, mice with acute DSS-colitis and TNBS-relapsing colitis produce elevated levels of IL-21, and administration of a neutralizing IL-21R fusion protein to DSS-treated mice attenuates the ongoing colitis and reduces the production of Th17-related cytokines." (PMID 22082127, 2011). "However, the role of the IL-21/IL-21R signaling axis in colitis of any origin and in collaboration with IFN-γ is not known." (PMID 30818341, 2019). "Similarly, immunodeficient mice adoptively transferred with CD4+IL-21−/− T cells develop less severe colitis, and mice treated in a prophylactic setup with a neutralizing IL-21R/Fc fusion protein or anti-IL-21 mAb are protected from both DSS and TNBS-induced colitis." (PMID 29849593, 2018). "Collectively, these findings indicated a novel and previously unknown role played by IL-21/IL-21R signaling in driving CD4+ T-cell responsiveness to IL-12 by enhancing the expression of IL-12Rβ2 in CD4+ T cells, thereby imprinting a TH1-biased immunity during bacterial-induced colitis." (PMID 38498592, 2024). "Moreover, WT mice, given a neutralizing IL-21R/Fc fusion protein, exhibit an amelioration of experimental colitis as compared to control mice; however, this was not confirmed by our experiments, which could be due to strain-specific alterations or due to the pharmacologic properties of the molecule." (PMID 28066428, 2016).
viral infection (12 papers, 2013 to 2026). "To determine if the increased susceptibility to viral infection of the IL-21R KO mice could be due to an inherent altered expression of PRRs we measured mRNA levels of TLR2, TLR3, TLR9, MDA-5, AIM-2, DAI, RIG-I and IFI16." (PMID 24358128, 2013). "During a chronic viral infection or under IL-2-deprived conditions IL-21R signaling is critical for preventing CD8+ T-cell exhaustion." (PMID 34721405, 2021). "This is in keeping with works showing that during a chronic viral infection or under IL-2-deprived conditions, IL-21R signaling is critical for preventing CD8+ T-cell exhaustion." (PMID 34721405, 2021). "In acute viral infections, IL-21R signaling is essential for the proliferation and survival of activated CD8+ T cells as well as the generation of long-lived memory cells." (PMID 34721405, 2021). "In this study we investigated the role of IL-21 and the IL-21R in innate immunity to virus infections using a murine vaginal HSV-2 infection model." (PMID 24358128, 2013). "The purpose of this study was to investigate the role of IL-21 and IL-21R in the innate immune response to a virus infection." (PMID 24358128, 2013). "Here we used a mouse model of IL-21R-deficiency to evaluate the role for IL-21R signaling in vaccine-induced protection against RABV; i.e., an acute viral infection that relies on B cells for protection that has implications for global public health initiatives." (PMID 23516660, 2013). "Cells belonging to the innate immune system such as epithelial cells, NK, NKT cells and macrophages express the functional heterodimer IL-21R and respond to IL-21, thus they are potential targets for IL-21 in the innate stages of a viral infection (day 1-3 p.i.)." (PMID 24358128, 2013). "Thus, this short time period of virus infection may bypass any need for additional survival signals (i.e. IL-21R) to prolong CD8+ T cell function." (PMID 25849970, 2015). "However, it is possible that although the TFH cells generated in IL-21R-/- mice can drive a substantial germinal center reaction, they may lack certain functions that, while not absolutely critical for the GC reaction, are critical for viral infection." (PMID 25875847, 2015). "In a chronic virus infection model (e.g. LCMV clone 13) where virus persists over 35 days, IL-21R KO CD8+ T cells exhibited a more prominent exhausted phenotype compared to WT mice, and viral loads were correspondingly higher." (PMID 25849970, 2015). "An important finding in this report is that in contrast to chronic viral infection models, IL-21R signaling is not required for acute antiviral immune responses and efficient virus clearance during primary IAV infection." (PMID 25849970, 2015). "In addition to its role in T-dependent B cell activation, IL-21R signals are also critical to maintain survival and prevent exhaustion of CD8+ T cells responding to chronic virus infection." (PMID 25849970, 2015). "Strikingly, this virus-driven Treg cell expansion was much more pronounced and longer lasting in mice lacking IL-21R expression, which suggested that the pro-inflammatory cytokine IL-21 restricted the proliferation of Treg cells in viral infections." (PMID 23696736, 2013). "The functional heterodimer IL-21R is highly expressed by cells from the innate immune system and IL-21 is known to increase IFN-γ production and cytotoxicity of NK cells, which are important effector cells in early control of viral infections." (PMID 24358128, 2013). "The importance of cell-intrinsic IL-21R signaling for the maintenance of CD8+ T cell functionality has been well documented and is considered as the primary effect of IL-21 promoting the immune control of chronic viral infections." (PMID 23696736, 2013).
Arthritis (11 papers, 2008 to 2025). Inflammation of a joint. "IL-21 blockade by anti-IL-21R or IL-21R deficiency controlled spontaneous arthritis in K/BxN mice." (PMID 34337086, 2021). "Recent studies observe that IL-21R transcript is expressed by synovial macrophages and fibroblasts from RA patients but not from patients with osteoarthritis (OA) and IL-21R deficiency in the K/BxN mouse model of inflammatory arthritis is sufficient to protect it from arthritis." (PMID 23176102, 2012). "In the K/BxN model of spontaneous autoantibody mediated arthritis, K/BxN IL-21R−/− mice are protected from initiation of arthritis or autoantibody development." (PMID 30233580, 2018). "Treating these mice with an IL-21R.Fc fusion protein reduced the clinical signs of collagen-induced arthritis, decreased antibody levels and decreased IL-6 levels thereby demonstrating a pathogenic role for IL-21 in mouse models of RA." (PMID 30233580, 2018). "In the arthritis research reports, blockade of IL-21R.Fc reduced the clinical and histologic signs of CIA." (PMID 29182672, 2017). "Secondly, we used IL-6-/- x IL-21R-/- mice to study the in vivo effects of cytokine pathway blockade on Th17 differentiation and development of experimental arthritis." (PMID 28158305, 2017). "Earlier work of our group showed reduced arthritis severity in IL-21R-/- mice as compared to WT controls, the present study confirms these data." (PMID 28158305, 2017). "The T cell-driven AIA model was induced in WT, IL-6-/-, IL-21R-/-, and IL-6-/- x IL-21R-/- mice, and the number of Th17 cells in draining LNs was assessed two days after arthritis onset." (PMID 28158305, 2017). "Similar to our results, they demonstrated that IL-21R on B cells was sufficient for the development of arthritis." (PMID 27535236, 2016). "Arthritis started to develop in WT mice about 1 week after the boost whereas Il21r KO mice were highly resistant to the development of arthritis." (PMID 27535236, 2016). "Blocking the IL-21 pathway with IL-21R-Fc fusion protein has been shown to ameliorate the clinical and histologic signs of arthritis and dramatically reduce total IgG1 and inflammatory cytokines levels." (PMID 23176102, 2012). "Another group reported attenuated clinical arthritis scores and lower total serum IgG1 levels in CIA DBA1 mice and in Lewis rats induced for antigen induced arthritis (AIA) following IL-21R.Fc treatment." (PMID 32332730, 2020).
inflammatory bowel disease (11 papers, 2008 to 2022). A spectrum of small and large bowel inflammatory diseases of unknown etiology. "Studies have shown that IL-21R activation can inhibit Th1 and activate Th2, Th17, and Treg responses, which can help alleviate DSS-induced acute colitis, and IL-21R may be a new target for the treatment of inflammatory bowel disease and other enterodynamic disorders." (PMID 35774604, 2022). "Serum level of IL-21 is increased in patients with inflammatory bowel diseases (IBD), suggesting that IL-21/IL-21 receptor (IL-21R) signaling may be involved in the pathogenesis of IBD." (PMID 27545302, 2016). "Furthermore, the observation for upregulated IL-21R was also found in NK cells of patients with inflammatory bowel disease (IBD), suggesting that the expression of IL-21R on NK cells may be upregulated in response to chronic inflammatory reactions such as IBD or ESCC." (PMID 20029417, 2010). "In human material, IL-21 and IL-21R expression was investigated by in situ hybridization (ISH) and immunohistochemistry (IHC) in noninflammatory bowel disease (non-IBD) controls and patients with CD." (PMID 29849593, 2018).
diabetes (10 papers, 2008 to 2025). "In contrast, IL-21R-deficient 8.3 mice have reduced diabetes incidence and reduced SOCS1 reporter activity in islet CTLs." (PMID 31653894, 2019). "Recent data provides a compelling case for IL-21 as a critical immune regulator of T1D pathogenesis, since IL-21 and IL-21R deficient NOD mice are almost completely protected from diabetes, depending on the animal house." (PMID 31653894, 2019). "In the present study we show that presence of diabetes is associated with a general T cell attenuation characterized by reduced overall T cell, Th17, IL-21R+, Treg’s and TLR4+ T cell count, while the monocyte population shows enhanced TLR4 expression." (PMID 27095356, 2016). "We found that NOD mice deficient in the IL-21R were completely protected from diabetes (n = 15, 0% incidence) during the 48-week observation period." (PMID 18773086, 2008). "In addition, an association between polymorphisms of the IL-21R with diabetes in Japanese patients, and with SLE in a European-derived cohort were documented." (PMID 40979706, 2025). "Furthermore, IL-21 overexpression in pancreatic β-cells led to increased expression of inflammatory mediators such as IL-17A, IL-17F, IFN-γ, MCP-1, MCP-2, and IP-10, whereas IL-21R deficiency conferred protection against insulitis and diabetes in NOD mice." (PMID 40979706, 2025). "Furthermore, in a virus-induced mouse model for type-1 diabetes on the NOD background, a dramatic reduction in diabetes incidence in IL-21R-deficient mice was reversed with the addition of IL-21 receptor sufficient dendritic cells." (PMID 38720888, 2024). "Furthermore, we recently demonstrated in a cohort of 20 subjects at risk to develop diabetes an inverse correlation of the frequency of IL-21R+ T cells with increased body mass index." (PMID 27095356, 2016). "Further the positive correlation between high CFR and elevated CD8+IL-21R T cells suggests that these IL-21R+ T cells may be associated with better cardiac function in diabetes." (PMID 27095356, 2016). "In addition to these reports, an association between microsatellite polymorphisms of the IL-21R and diabetes in Japanese patients, between rs3093301 and rs2285452 in the IL-21R gene region and SLE in the European-derived cohort were documented." (PMID 23889847, 2013). "Moreover, IL‐21, the central cytokine produced by Tfh and Tph cells, appears to play a pivotal role in autoimmune diabetes: IL‐21R‐deficient NOD mice are protected from diabetes, whereas IL‐21 overexpression in beta cells precipitates the disease in diabetes‐resistant mice." (PMID 32697399, 2020). "Furthermore, it should be noted that it is possible that diabetes resistance in IL-21R-deficient NOD mice may be attributed to still unidentified protective alleles in the C57BL/6 genome, as has been identified in disease-resistant IFNγ knockout NOD mice." (PMID 18773086, 2008). "The authors noted the failure of IL-21R deficient dendritic cells to acquire CCR7 which is needed for their migration to lymph nodes, may explain the reduction in the diabetes onset." (PMID 38720888, 2024). "Diabetes incidence in female NOD8.3/IL21R mice was significantly lower than wildtype NOD8.3 mice, in accordance with the previously observed protection in IL-21 or IL-21R deficient NOD mice." (PMID 31653894, 2019). "Thus, our novel findings in established T2D extend our previous observations in patients at risk of developing T2D that the systemic presence of IL-21R+ CD4 T cells is reduced in obesity, pre-diabetes and T2D." (PMID 27095356, 2016). "The decreased number of effector T cells we observed in IL-21R deficient mice underlies the protection against diabetes in the absence of IL-21 signaling." (PMID 18773086, 2008). "It was demonstrated that IL-21R is essential for pancreas DCs to acquire the CCR7 chemokine receptor and migrate into the draining lymph node, thereby breaking diabetes resistance in type 1 diabetes." (PMID 37628738, 2023).
diabetes (continued). "Since T cell effector function was diminished when the IL-21R was absent, we asked whether IL-21 plays a role in precipitating clinical diabetes in NOD mice." (PMID 18773086, 2008). "In mice, IL-21 is overproduced in models of autoimmune diabetes, and deficiency in IL-21R was found to prevent the development of diabetes in non-obese diabetic (NOD) mice, while transgenic expression of IL-21 in pancreatic islets was sufficient to trigger diabetes in non-autoimmune C57BL/6 mice." (PMID 38164992, 2024).
psoriasis (8 papers, 2013 to 2025). An autoimmune condition characterized by red, well-delineated plaques with silvery scales that are usually on the extensor surfaces and scalp. "Furthermore, our results show that the genes mediating the development of IBD in psoriasis may be associated with the following genes CSF2RA/SOCS1/PTPN2/STAT3/IL21R, which has implications for the exploration of co-morbid targets in PsO combined with IBD." (PMID 38803495, 2024). "They found increased IL-21 and IL-21 receptor (IL-21R) expression in lesional skin and peripheral blood samples of psoriasis patients​." (PMID 40161116, 2025). "IL-21 is a cytokine still under current investigations regarding its entire part in psoriasis, with high amounts of IL-21 receptor (IL-21R) revealed in keratinocytes." (PMID 38793117, 2024). "To verify the role of IL-21 in the progression of psoriasis, we administrated the anti-IL-21R antibody to neutralize the IL-21 signaling pathway through IMQ-induced psoriasis-like BALB/c mouse models." (PMID 32684837, 2020). "Our result revealed that an increased number of CD4+ T cells secrete IL-21 and express IL-21R in the PBMCs derived from psoriasis patients." (PMID 31440249, 2019). "The results of western blotting and immunohistochemical staining confirmed the higher expression of IL-21 and IL-21R in the protein level of psoriasis patients compared with the healthy individuals." (PMID 31440249, 2019). "Our results showed that IL-21R is highly expressed in PBMCs and in the lesional skin of psoriasis patients, and that IL-21 can promote CD4+ T cell proliferation and Th17 cell differentiation and also the secretion of IL-17A and IL-22." (PMID 31440249, 2019). "The association at IL21 is substantiated biologically by previous work demonstrating upregulation of IL21 and its receptor IL21R in skin lesions from psoriasis and atopic dermatitis (AD) patients." (PMID 28199695, 2017). "IL-21 deficient mice showed decreased severity in these diseases models whereas in the imiquimod (IMQ)-induced psoriasis model, inflammation was not alleviated in the IL-21R deficient mice." (PMID 31440249, 2019). "As the main source of IL-17A in the psoriasis mouse model is γδT cells, not Th17 cells, and IL-21 can inhibit the secretion of IL-17A in γδT cells, no alleviation of inflammation can be observed in IL-21R deficient mice." (PMID 31440249, 2019). "The mRNA levels of IL-21, IL-21R, IL-17A, IL-22, IL-23, RORγt, and IFN-γ were increased, whereas the mRNA level of Foxp3 was decreased in the PBMCs of psoriasis patients." (PMID 31440249, 2019). "The dysregulation of IL-21 and IL-21R plays a role in multiple immune-mediated diseases, including SLE, psoriasis, RA and other chronic inflammatory diseases." (PMID 23889847, 2013). "Moreover, neutralizing IL-21R with anti-mouse IL-21R antibody significantly reduces IMQ-mediated accumulation of MDSCs in skin lesions and splenic Th17 cells, indicating targeting IL-21 is a therapeutic approach for psoriasis." (PMID 32684837, 2020). "Neutralizing IL-21R by antibody reduces IMQ-induced epidermal thickening through downregulating the infiltration of MDSCs and Th17 cells, suggesting the accumulation of MDSCs exerts important function for the pathogenesis of psoriasis and IL-21 may be a potential therapeutic target in psoriasis." (PMID 32684837, 2020).